ERBB2 (erb-b2 receptor tyrosine kinase 2)
Diseases named in the same sentence as ERBB2 in open-access papers (continued):
Sharing a sentence is not in itself a finding about the gene and the disease.
breast cancer (continued). "In conclusion, pyrotinib is a potential neoadjuvant agent for patients who are heavily pretreated and harbor both ERBB2 amplification and ERBB2 mutant in locally advanced breast cancer." (PMID 34722261, 2021). "FGFR1-3 inhibition with AZD4547 has been reported to selectively target mammary stem cells and TIC populations in an ErbB2-overexpressing breast cancer mouse model." (PMID 33772015, 2021). "CNA analysis confirmed recurrence-specific ERBB2 amplification and is consistent with previous studies of endocrine therapy-treated breast cancers selecting for HER2 signaling in more advanced tumors." (PMID 33407744, 2021). "ERBB2 showed the highest expression-driven dependency in the on-label breast cancer cells (R = −0.68, FDR = 2.5E − 3) along with significant expression-driven dependency in ovarian cancer cell lines (R = −0.53, FDR = 0.038)." (PMID 34552204, 2021). "EphA2, which is known to augment ErbB2-induced mammary tumorigenesis, was increased 4-fold in the Pparγ1+/+ ErbB2 mammary tumors." (PMID 33946495, 2021). "In the literature, RAD21 (Gene Entrez ID 5885) was validated as a luminal, basal, and ERBB2 breast cancer gene marker." (PMID 34573857, 2021). "Twenty-five percent of breast cancer over-expressed ERBB2, which conferred a more aggressive phenotype and targeted therapy was needed." (PMID 33796128, 2021). "Trastuzumab is a humanized monoclonal antibody against the extracellular domain of an oncoprotein identified as human epidermal growth factor receptor 2 (HER2/ERbB2), which is highly relevant in prognosis in breast cancer." (PMID 34540917, 2021). "In this study, we have shown that a CNN trained on a primary breast tumor tissue morphology is able to learn patterns predictive of breast cancer ERBB2 gene amplification status as assessed by chromogenic in situ hybridization." (PMID 33597560, 2021). "ERBB2-induced breast cancer cell invasion has been documented to be caused by the TOM1L1-derived membrane delivery of MT1-MMP, and ERBB2 and TOM1L1 are frequently coamplified in the breast." (PMID 34917619, 2021). "The use of next-generation sequencing (NGS) to measure ERBB2 CN in breast cancer is approved by the United States Federal Drug Administration as a companion diagnostic." (PMID 33710417, 2021). "The ERBB2 chromatin of HER2-high epithelial-like breast cancer cells and HER2-low mesenchymal-like cells were found to be open/active and closed/inactive, respectively." (PMID 34575017, 2021). "First, Infiltration of F4/80+ macrophages into the mammary tumors of transgenic mice, which are known to augment ErbB2-induced tumor progression, was reduced by Pparγ1 deletion." (PMID 33946495, 2021). "ErbB2 overexpression is mainly known from different carcinomas like breast cancer or gastric cancer." (PMID 32591879, 2021). "Breast cancer is classified based on expression of receptors which include estrogen receptor (ER), human epidermal growth factor (ERBB2) and progesterone receptor (PR)." (PMID 33670942, 2021). "Forexample, Her2/ErbB2/neu is a tyrosine kinase, which is overexpressedin 20% of breast cancers along with some gastrointestinal and othercancer types." (PMID 34778614, 2021). "ErbB2-overexpressing breast cancer cells with low CHIP expression exhibited higher endoplasmic reticulum stress inducibility." (PMID 34439093, 2021). "The receptor tyrosine kinase EPH receptor A2 (EphA2), a member of the Eph RTK family, is overexpressed in aggressive breast cancer and EphA2 forms a complex with ErbB2 thereby enhancing ErbB2-induced tumor onset and progression." (PMID 33946495, 2021). "Almost one-third of breast cancers overexpress the ErbB2 tyrosine kinase receptor (Her2 in humans, Neu in rats)." (PMID 34393784, 2021). "Triple-negative breast cancer (TNBC; defined by ER, PR, and HER2/ERBB2-negativity) is a clinically defined subgroup of breast cancer, constituting approximately 10–15% of cancers in Western countries." (PMID 33568222, 2021).
breast cancer (continued). "Herein, genetic deletion of Pparγ1 in a murine model of human ErbB2-mediated breast cancer, the rate of tumor progression and death was significantly reduced." (PMID 33946495, 2021). "Human epidermal growth factor receptor 2 (HER2/erbB2/neu) is a prognostic factor and biomarker for detecting mammary tumor malignancy." (PMID 34566312, 2021). "Lapatinib is the first dual inhibitor of EGFR and ERBB2/HER2 for treating ERBB2-positive breast cancer, whereas brigatinib is a mixed inhibitor of ALK and EGFR used for the treatment of metastatic NSCLC." (PMID 34607583, 2021). "Our in vitro proliferation data demonstrated synergistic inhibition of proliferation of ErbB2-overexpressing breast cancer cell lines with Bortezomib and Trastuzumab." (PMID 34439093, 2021). "ERBB2 amplification is a predictive biomarker of response for HER2 targeted therapy in breast cancer." (PMID 33968723, 2021). "For this purpose, they selected the MDA-MB-453 cell line with overexpression of erythroblastic oncogene B-2 (ErbB-2, also as known human epidermal growth factor receptor 2 or HER-2/neu) compared to the other human breast cancer cell lines." (PMID 34715860, 2021). "Currently, chemotherapy, endocrine therapy, and ERBB2-targeted antibody or small molecule inhibitor therapy combined with chemotherapy are mainstays in breast cancer treatment." (PMID 34842655, 2021). "This same trend was observed with HER2/ERBB2 overexpression in disseminated breast cancer tissue correlating with worse outcomes." (PMID 33987095, 2021). "The ERBB1/2 inhibitor, lapatinib, led to the reversal of the aberrant ARE-mediated process in ERBB2-amplified breast cancer cells." (PMID 34535639, 2021). "There are three major breast cancer subtypes: luminal ER positive (including luminal A and luminal B), ERBB2 enriched and basal-like or triple-negative." (PMID 34356858, 2021). "Metastatic HR+ and ERBB2+ breast cancer has a median overall survival of 4 to 5 years and 5 years, respectively, while metastatic TNBC has a median overall survival of 10 to 13 months." (PMID 33670942, 2021). "First, the CNA profile of breast cancer was selected from the four-level hierarchy, which listed ERBB2 among the top five genes that exhibits duplication frequency of 2.06, 2.06 and 16.67% in COSMIC, CCLE and TWBC, respectively." (PMID 34259866, 2021). "Genetic deletion of Pparγ1 slowed the rate of tumor progression and death from ErbB2-induced mammary tumors." (PMID 33946495, 2021). "The RAS-MAPK kinase pathway is one of the signaling cascades activated by ERBB2 and is suggested to be in concert with the PI3K/AKT pathway in ERBB2-positive breast cancer." (PMID 34535639, 2021). "Herceptin, an antibody-based therapy directed against the extracellular domain of ERBB2, has shown limited therapeutic efficacy against ERBB2-positive breast cancer." (PMID 34283045, 2021). "To investigate the role of ERBB2 in autophagy, we knocked out ERBB2 in the breast cancer cell line SKBR3 expressing a high level of ERBB2 by a double nickase-based CRISPR/Cas9 system." (PMID 33801244, 2021). "In various tumor entities, particularly breast cancer and gastric cancer, ErbB2 is overexpressed due to ErbB2 gene amplification." (PMID 32591879, 2021). "Growth rate of established ErbB2 mammary tumors upon Cre-mediated deletion of Pparγ1 was determined as well." (PMID 33946495, 2021). "The MMTV-Neu model of HER2-positive breast cancer is driven by targeted expression by the MMTV promoter of the Neu (also known as ErbB2) oncogene to the mammary gland." (PMID 34638488, 2021). "Adenoviral gene E1A that interferes with the transcription of erbB-2 can use to inhibit the transcription of overexpressed oncogenes in the treatment of ovarian and breast cancer." (PMID 34888205, 2021).
breast cancer (continued). "A bright fluorescent signal throughout an entire mammary tumor was indicative that the MMTV-Flp transgene was active and that the recombined Rosa26CAG-FSF-CreERT2 was functional in ERBB2/neu-expressing mammary tumor cells in vivo." (PMID 34675248, 2021). "Its role as a regulator of ErbB3 makes EBP1 a contributor to breast cancer progression and treatment resistance, as it controls, for example, the ErbB2 protein levels and tamoxifen sensitivity in breast cancer cells." (PMID 34948097, 2021). "The conclusion of ERBB2 inhibition of autophagy was drawn mainly based on the observation that lapatinib, an inhibitor for both EGFR and ERBB2 tyrosine kinases, increased autophagy in ERBB2-expressing breast cancer cells." (PMID 33801244, 2021). "In breast cancer, the most common cancer in women worldwide, ERBB2 is overexpressed in about 11–30% of all cases." (PMID 33801244, 2021). "HER2 (ERBB2) monoclonal antibody trastuzumab has achieved exciting results in the treatment of breast cancer." (PMID 34209278, 2021). "Triple-negative breast cancer (TNBC), a heterogeneous breast cancer subtype, lacks endocrine estrogen receptor (ER) and progesterone receptor (PR) and human epidermal growth factor receptor 2 (HER2, encoded by ERBB2)." (PMID 34109118, 2021). "We therefore assessed the functional consequences of ECD KD on key in vitro oncogenic traits of ErbB2-overexpressing breast cancer cell lines." (PMID 33941617, 2021). "Loss of Gene 33 expression, which is associated with higher ErbB2 activity, confers resistance to the EEBB2 neutralizing antibody Herceptin in breast cancer." (PMID 34206547, 2021). "The humanized monoclonal antibody Trastuzumab is used as a standard targeted therapy for ErbB2-overexpressing breast cancer patients." (PMID 34439093, 2021). "Basal breast cancers that lack the expression of both steroid hormone receptors and ERBB2 represent approximately one sixth of all cases." (PMID 34527184, 2021). "We then chose to focus this study on ERBB2, an important molecule in the pathogenesis and targeted therapy of ERBB2/HER2 + breast cancer." (PMID 34535639, 2021). "Human epidermal growth factor receptor 2 (HER2), also known as erythroblast leukemia virus oncogene homolog 2 (ErbB2), is overexpressed in 20–25% of breast cancers." (PMID 34790121, 2021). "In order to determine the signal transduction pathways maintained by Pparγ1 in the ErbB2 mammary tumors, we conducted Kyoto Encyclopedia of Genes and Genomes (KEGG) pathway analysis of RNA-seq from the tumors." (PMID 33946495, 2021). "Meanwhile, in vivo assays further corroborated the oncogenic function of circ-ERBB2 in HER2-positive breast cancer." (PMID 34732216, 2021). "Taken together, these results suggest that chromatin activity of the ERBB2 gene governs ERBB2 gene expression in breast cancer." (PMID 34575017, 2021). "Conclusively, our data expounded that circ-ERBB2 was increased in tumor tissues of HER2-positive breast cancer patients and its expression was positively correlated with TFAP2C expression." (PMID 34732216, 2021). "As the most potent oncogene of the EGFR family members, ERBB2 is over-expressed in the tumors of many types of cancers such as breast cancer, gastric cancer, colon cancer, bladder cancer, and biliary cancer." (PMID 33801244, 2021). "The current studies extend our understanding of Her2-function by identifying the critical role for Pparγ1 in mediating ErbB2-mammary tumor progression in vivo." (PMID 33946495, 2021). "ErbB2-targeted drugs cause cardiac dysfunction that is exacerbated when combined with anthracycline chemotherapy for HER2-positive breast cancer." (PMID 34790121, 2021). "We first trained a CNN to predict breast cancer ERBB2 status on 693 H&E-stained patient samples from the FinProg series." (PMID 33597560, 2021). "Depending on the presence of oncological markers on the malignant cell surface, three type of breast cancer can be distinguished: ER/PR+, ErbB2+ and triple negative." (PMID 34944558, 2021).
breast cancer (continued). "As selected examples, targeted disruption of β1-integrins in a mouse model of human breast cancer leads to a dormant phenotype and blocks tumor induction β4 integrins promotes mammary tumorigenesis in vivo via upregulation of ErbB2 signaling.." (PMID 35936112, 2021). "In the case of HER2-positive breast cancer, where upregulation of the receptor tyrosine kinase HER2 (ErbB2) occurs in ~20% of all tumors, both trastuzumab- and lapatinib-based regimens offer significant clinical benefit." (PMID 34239043, 2021). "We intersected an updated list of 564 over-expressed breast cancer ARE-mRNAs based on our previous analysis with a list of genes that selectively over-expressed in ERBB2-positive invasive ductal breast cancer tissues (TCGA database)." (PMID 34535639, 2021). "About 15–20% of all breast cancers (BCs) are defined human epidermal growth factor receptor 2 (HER2)-positive, based on the overexpression of HER2 protein and/or amplification of ERBB2 gene." (PMID 36046143, 2021). "For example, amplification including the ERBB2 gene in the SK-BR3 breast cancer cell line spanned a 3 Mb region with multiple translocations on chromosome eight." (PMID 34527193, 2021). "In other words, mesenchymal breast cancer cells exhibit low ERBB2 gene expression compared to epithelial-like breast cancer cells." (PMID 34575017, 2021). "As ErbB2 overexpression in most breast cancer patients represents increased transcription from an amplified ErbB2 gene locus, the oncogenic drive is likely to depend on efficient processing of the mRNA for the driver oncogene ErbB2." (PMID 33941617, 2021). "Our study also showed that DEPTOR is indispensable for the proliferation and survival of ErbB2-positive breast cancer cells." (PMID 33995662, 2021). "In this research, we identified the abnormally elevated circ-ERBB2 in HER2-positive breast cancer and authenticated that the interference with circ-ERBB2 repressed tumor cell growth." (PMID 34732216, 2021). "PRL in breast cancer cells via PRLR/JAK2 can also induce phosphorylation of ERBB2/HER2, which in turn activates the downstream RAS/MEK/ERK pathway required for ERα phosphorylation." (PMID 34572912, 2021). "As a suppressor, ectopic expression of miR-205 inhibits cell anchorage-independent growth and proliferation by repressing expression of ErbB3, which is a component of the most potent oncogenic complex ErbB2/ErbB3 heterodimer in breast cancer." (PMID 33413418, 2021). "Nectin-4, upregulated in various cancer cells, cis-interacts with ErbB2 and its trastuzumab-resistant splice variants, p95-ErbB2 and ErbB2∆Ex16, enhancing DNA synthesis through the PI3K-AKT signaling in human breast cancer T47D cells in an adherent culture." (PMID 33795719, 2021). "Which is the prognostic value of p140Cap in the other subtypes of breast cancer, except for the ErbB2-amplified tumors?" (PMID 34708040, 2021). "Forkhead box protein P3 (FOXP3) is involved in regulatory T (Treg) cell development and inhibits tumorigenicity by downregulating oncogenes such as HER2/ErbB2 in breast cancer." (PMID 33968766, 2021). "There are five common molecular subtypes of breast cancer: luminal A, luminal B, basal, ERBB2, and normal-like." (PMID 34573857, 2021). "Overexpression of HER2 occurs in 20–30% of all breast cancer tumors (known as HER2-positive breast cancers), mostly due to ERBB2 gene amplification." (PMID 34575017, 2021). "Enrichment analyses of genes associated with both breast cancer DMFS and OS showed their involvement in natural killer cell mediated cytotoxicity, drug metabolism, muscle filament, ERBB2 and leptin signaling, aminoacid synthesis and B cell receptor signaling." (PMID 35096604, 2021). "Our results suggest that CHIP-dependent alterations in the association of ErbB2 with molecular chaperones are an important mechanism to promote the Golgi to surface transport of newly synthesized ErbB2 in ErbB2-overexpressing breast cancer cells." (PMID 34439093, 2021).
breast cancer (continued). "In this study, we found that in ErbB2-positive breast cancer tissues and cells, DEPTOR is present on the cell membrane where it interacts with ErbB2 (residues 1026 to 1240) via its PDZ domain." (PMID 33995662, 2021). "TNBC has a poor prognosis, with a 5-year breast cancer-specific survival rate of 85% for stage I tumors (compared to 99% and 95% for hormone or ERBB2-positive groups, respectively)." (PMID 34649623, 2021). "In conclusion, we have found OXTR overexpression induces ERBB2+ mammary tumors through activation of PRL/p-STAT5 pathway." (PMID 34099636, 2021). "Overexpression of ERBB2 in human breast cancers enhances glycolysis by increasing the expression of a glycolytic enzyme LDHA." (PMID 34685621, 2021). "NK-92 cells have also been redirected to target ErbB2 in breast cancer cell lines; SKBR3 breast cancer cells were specifically lysed by NK-92- ErbB2 targeting CAR cells compared to NK-92 parental cells in-vitro." (PMID 33923528, 2021). "Breast cancer and ovarian cancer are both associated with mutations and/or overexpression/amplification in certain genes (e.g. BRCA1, BRCA2, PIK3C, ERBB2, etc.)and aberrations in related pathways, which exhibits a risk of co-occurrence in women." (PMID 34181736, 2021). "We next sought to explore the application of NGS detection for predicting ERBB2 copy number amplification in breast cancer patients." (PMID 33893247, 2021). "Functionally, circ-ERBB2 knockdown restrained HER2-positive breast cancer cell proliferation, migration, invasion and accelerated cell apoptosis." (PMID 34732216, 2021). "Both pathways are hyperactive in ErbB2-overexpressing breast cancers and appear critical to maintain the oncogenic drive." (PMID 34439093, 2021). "Upregulation of another member of the TOM1 family proteins, TOM1-L1, enhances v-erb-b2 avian erythroblastic leukemia viral oncogene homolog 2 gene (ERBB2)-induced invasion of breast cancer cells, in a process that involves TOLLIP." (PMID 33718385, 2021). "The relationship of OXTR, hyperprolactinemia, and ERBB2 expression in breast cancer is established in this study." (PMID 34099636, 2021). "In breast cancer, high levels of ErbB2 are correlated with poor prognosis, lymph node metastasis, and drug resistance." (PMID 33995662, 2021). "Ectopic CHIP expression in ErbB2-overexpressing breast cancer cell lines suppressed the in vitro oncogenic traits and in vivo xenograft tumor growth." (PMID 34439093, 2021). "TNBC is an aggressive form of breast cancer with poor outcomes compared to hormone or anti-ERBB2 therapy responsive groups, partly because patients with TNBC do not benefit from treatments that target the hormone receptors or ERBB2." (PMID 34649623, 2021). "This suggests that the expression of the ERBB2 gene in epithelial-like breast cancer cells is higher than that of mesenchymal-like breast cancer cells." (PMID 34575017, 2021). "In the ERBB2-amplified subgroup of breast cancer patients, p140Cap expression predicts a significantly lower probability of developing distant events." (PMID 34708040, 2021). "The cancer-centric cluster of the amplified oncogenes indicated that ERBB2/EGFR/AKT is predominately found in breast cancer." (PMID 34535639, 2021). "Taken together, this study provides a novel approach for the treatment of ERBB2-positive breast cancer by targeting ATG12-dependent autophagy." (PMID 33801244, 2021). "At the molecular level, breast cancer molecular signatures include the activation of human epidermal growth factor receptor 2 (HER2, encoded by ERBB2), the activation of hormone receptors (estrogen receptors and progesterone receptors), and BRCA mutations." (PMID 35096628, 2021). "It was shown that HER2+ breast cancer patients who had developed resistance to trastuzumab showed significantly higher levels of HER2/ERBB2 in their ctDNA when compared to those who benefitted from the treatment." (PMID 34359713, 2021).